APH1B (aph-1B gamma-secretase subunit)
Description:
Probable subunit of the gamma-secretase complex, an endoprotease complex that catalyzes the intramembrane cleavage of integral proteins such as Notch receptors and APP (amyloid-beta precursor protein). It probably represents a stabilizing cofactor for the presenilin homodimer that promotes the formation of a stable complex. Probably present in a minority of gamma-secretase complexes compared to APH1A.
Synonyms: APH-1b; PSFL; DKFZp564D0372; PRO1328; TAAV688; aph-1beta
Tractability: Small molecule: a drug acting on it is in phase 2 or 3 trials; a structure with a bound ligand is known; a high-quality ligand is known; it belongs to a druggable protein family. Antibody: its Gene Ontology location is reachable by antibodies, with high confidence; UniProt predicts a signal peptide or a membrane-spanning region. PROTAC: ubiquitination databases record sites on it; a small molecule that binds it is known.
Gene: Protein-coding gene on chromosome 15 (63,276,018 to 63,309,126, forward strand). Ensembl gene ENSG00000138613.
Subcellular location: Membrane
Pathways (Reactome):
Signal Transduction: Activated NOTCH1 Transmits Signal to the Nucleus; NOTCH2 Activation and Transmission of Signal to the Nucleus; NOTCH3 Activation and Transmission of Signal to the Nucleus; NOTCH4 Activation and Transmission of Signal to the Nucleus; NRIF signals cell death from the nucleus; Noncanonical activation of NOTCH3; Nuclear signaling by ERBB4; Regulated proteolysis of p75NTR; TGFBR3 PTM regulation
Disease: Constitutive Signaling by NOTCH1 HD+PEST Domain Mutants; Constitutive Signaling by NOTCH1 PEST Domain Mutants
Developmental Biology: EPH-ephrin mediated repulsion of cells
Metabolism of proteins: Amyloid fiber formation
Gene Ontology:
Molecular function: endopeptidase activator activity; protein binding; protein-macromolecule adaptor activity
Biological process: amyloid precursor protein catabolic process; amyloid-beta formation; Notch receptor processing; protein processing; Notch signaling pathway; proteolysis
Cellular component: gamma-secretase complex; membrane; transport vesicle; endoplasmic reticulum membrane; endosome membrane; Golgi membrane; plasma membrane
Genetic constraint (gnomAD): Loss-of-function variants: 29 observed, 29.8 expected, observed/expected ratio (o/e) 0.97, 90% interval 0.72 to 1.33. The upper end of that interval is the gene's LOEUF score, 1.33, which puts it in group 5 of 6, group 1 being the genes least tolerant of losing a copy. Missense variants: 305 observed, 321.86 expected, observed/expected ratio (o/e) 0.95, 90% interval 0.86 to 1.04. Synonymous variants: 141 observed, 127.89 expected, observed/expected ratio (o/e) 1.1, 90% interval 0.96 to 1.27.
Homologues: Orthologues: chimpanzee APH1B (100% identical), macaque APH1B (96% identical), pig APH1B (86% identical), dog APH1B (85% identical), guinea pig APH1B (85% identical), mouse Aph1b (84% identical), rat Aph1b (83% identical), rat Aph1bl2 (83% identical), mouse Aph1c (81% identical), rabbit APH1B (77% identical), zebrafish aph1b (63% identical), Drosophila melanogaster aph-1 (42% identical), and 1 more. Paralogues in human: APH1A (57% identical).
Diseases named in the same sentence as APH1B in open-access papers:
APH1B is named in the same sentence as 30 diseases in open-access papers, as found by Europe PMC text mining. Sharing a sentence is not in itself a finding about the gene and the disease. The quoted sentences say what the papers report.
Alzheimer disease (7 papers, 2008 to 2025). A progressive, neurodegenerative disease characterized by loss of function and death of nerve cells in several areas of the brain leading to loss of cognitive function such as memory and language. "Protein tyrosine kinase 2β (PTK2B)/clusterin (CLU) and membrane-spanning 4A (MS4A) were significantly associated with the onset of all-cause dementia, whereas aph-1 homolog B (APH1B) was specifically linked to Alzheimer's disease." (PMID 40949174, 2025). "We have tested for association of premature coronary atherosclerosis with a non-synonymous single-nucleotide polymorphism (SNP) in the γ-secretase component APH1B (Phe217Leu; rs1047552), a SNP previously linked to Alzheimer's disease." (PMID 18987747, 2008). "Other known Alzheimer's disease–associated genes, BIN1, TREM2, ZCWPW1, and APH1B, were also replicated in our time-to-event GWAS." (PMID 40949174, 2025). "In the Alzheimer’s disease pathway, we found genes up-regulated (Apbb1, Atf6, Cacna1d, Calm3, Casp7, Itpr1, Lpl, and Ppp3ca) and down-regulated (Aph1b, Bid, Cycs, Fadd, Fas, and Nae1)." (PMID 28513549, 2017). "Several downregulated genes, such as APH1B and NDUFA4, were involved in “Alzheimer’s disease” pathway." (PMID 40816274, 2025).
dementia (3 papers, 2021 to 2025). Loss of intellectual abilities interfering with an individual's social and occupational functions. "For dementia-related phenotypes, the expression of APH1B from blood eQTL data was strongly SMR association with increased AD risk (PSMR = 8.16 × 10−19)." (PMID 41296471, 2025). "The SNPs rs876461 (PRKD3; P = .02), rs117618017 (APH1B; P = .03), rs4844610 (CR1; P = .04), rs7584040 (BIN1; P = 2 × 10–3), rs11168036 (HBEGF; P = 8 × 10–3), rs143429938 (CLU/MIR6843; P = .04), and rs8064326 (KCTD2; P = 3 × 10‐4) were independently associated with incident dementia." (PMID 33532541, 2021).
breast carcinoma (2 papers, 2013 to 2023). "We found no preference for any of the subunit variants (PS1/PS2 and Aph1a/Aph1b) over the other in our sample set of breast cancer tissues." (PMID 24223915, 2013). "In conclusion, this is to our knowledge the first report describing mRNA expression levels of γ-secretase subunits PS1, PS2, Aph1a, Aph1b, PEN-2, and NCT in breast cancer tissues." (PMID 24223915, 2013). "There was a significant association between the low expression levels of PS1, Aph1a, Aph1b, and NCT and poor breast cancer specific survival." (PMID 24223915, 2013). "Our results are in a full agreement with those findings: The mRNA expression of Aph1b, PEN-2, and NCT were significantly lower in breast cancer cases with high tumor grade and there was a significant association between high expression level of γ-secretase complex and hormonal receptors." (PMID 24223915, 2013).
atherosclerosis (1 paper, 2008). A disease characterized by the build-up of fatty material and calcium deposition in the arterial wall resulting in partial or complete occlusion of the arterial lumen. "Our results show that, remarkably, only male individuals with atherosclerosis seem to be associated with the APH1B Phe217Leu variation." (PMID 18987747, 2008). "The APH1B Phe217Leu variation may thus play a dual role by affecting atherosclerosis as well as AD pathogenesis, suggesting that the two diseases have converged and that the γ-secretase signalling pathway is a susceptibility pathway for vascular complications." (PMID 18987747, 2008).
behavioral disorders (1 paper, 2025). "Notably, aph1b (neurodevelopmental disorders) and st3gal3 (intellectual disability and behavioral disorders) were implicated in disrupted synaptic maturation." (PMID 41310639, 2025).
Brain atrophy (1 paper, 2021). Partial or complete wasting (loss) of brain tissue that was once present. "In summary, our results show that dysregulated expression levels of APH1B in peripheral blood are associated with brain atrophy and Aβ deposition in AD." (PMID 34732252, 2021).
cervical cancer (1 paper, 2023). A primary or metastatic malignant neoplasm involving the cervix. "Previous studies have shown that High-risk HPV E7 maintains stemness in cervical cancer stem-like cells via APH1B." (PMID 37512088, 2023).
coronary atherosclerosis (1 paper, 2008). Atherosclerosis of the coronary vasculature. "Genotype and allele frequencies for the APH1B Phe217Leu variation in a Dutch case-control study on premature coronary atherosclerosis." (PMID 18987747, 2008). "In this study we show that the non-synonymous Phe217Leu polymorphism in the human APH1B gene is a male-specific risk factor for premature coronary atherosclerosis." (PMID 18987747, 2008). "Clinical and biochemical characteristics of the premature coronary atherosclerosis patients with and without the APH1B 217Leu allele." (PMID 18987747, 2008).
COVID-19 (1 paper, 2024). A disease caused by infection with severe acute respiratory syndrome coronavirus 2. "In addition, we used multiple machine learning methods to screen for five risk genes (KLF5, NSUN7, APH1B, GRB10 and CD4), which are used to predict COVID-19 severity." (PMID 38600309, 2024).
familial Alzheimer disease (1 paper, 2009). A degenerative disease of the brain that causes gradual loss of memory, judgment, and the ability to function socially. "These manipulations include introducing familial Alzheimer's disease L166P PS1 mutation, structural change in the Pen2 N-terminus, expressing Aph1B or Aph1A isoform, or pharmacological treatment (fenofibrate, ibuprofen)." (PMID 19924286, 2009).
gastric carcinoma (1 paper, 2021). A carcinoma that arises from epithelial cells of the stomach. "Interaction of hsa-miR-375 with both APH1B and CELF2 was experimentally confirmed in a gastric carcinoma sample." (PMID 34683087, 2021).
Hypertension (1 paper, 2008). The presence of chronic increased pressure in the systemic arterial system. "Functional consequences of reduced gene dosage of Aph1b were also observed in the APO-SUS/-UNSUS rat model, an animal model with complex features, including an impaired vasorelaxation response to adrenergic stimuli, which increases the risk for the development of hypertension and vascular diseases." (PMID 18987747, 2008).
Parkinson’s (1 paper, 2020). "APH1B is a transmembrane protein associated with risk of Alzheimer’s and Parkinson’s diseases." (PMID 30353169, 2020).
schizophrenia (1 paper, 2014). A major psychotic disorder characterized by abnormalities in the perception or expression of reality. "Neuregulin 1 (NRG1) and the γ-secretase subunit APH1B have been previously implicated as genetic risk factors for schizophrenia and schizophrenia relevant deficits have been observed in rodent models with loss of function mutations in either gene." (PMID 24891237, 2014). "Moreover, putative loss of function variants of APH1B, a crucial component of the γ-secretase complex, were found to aggregate with NRG1 risk alleles in schizophrenia patients and Aph1b-loss of function mutations in rodents display behavioural phenotypes that are relevant for schizophrenia." (PMID 24891237, 2014). "Moreover, our study suggests that schizophrenia linked cSNPs in TM domain of NRG1 and mutations in APH1B gene may contribute to the alteration of dendritic spines density observed in schizophrenia, linking APH1B and NRG1 misprocessing firmly to this disorder." (PMID 24891237, 2014).
tumor (2 papers, 2013 to 2022). "The association between subunit expression and tumor grade was significant for Aph1b (p = 0.033), PEN-2 (p = 0.005), and NCT subunits (p = 0.043)." (PMID 24223915, 2013).
APH1B also shares sentences with these, for which no sentence is quoted: cancer (2 papers); amyloid (1); aortic stenosis (1); autoimmune disease (1); cardiomyopathy (1); coronary artery disease (1); diabetes mellitus (1); familial Danish dementia (1); Intellectual disability (1); left ventricular hypertrophy (1); memory impairment (1); myocardial infarction (1); neuroblastoma (1); neurodevelopmental disorder (1); triple-negative breast carcinoma (1).